MMP1 (matrix metallopeptidase 1)
Diseases named in the same sentence as MMP1 in open-access papers (continued):
Sharing a sentence is not in itself a finding about the gene and the disease.
lung carcinoma (continued). "We also verified that lung CSC‐derived exosomes enhanced the migratory and invasive abilities of lung cancer cells; increased N‐cadherin, vimentin, MMP‐9 and MMP‐1 expression; and decreased E‐cadherin expression." (PMID 32396269, 2020). "However, MMP-1 expression has been reported in various kinds of malignant cells and is known to promote metastasis and invasion, and is also related to poor prognosis in breast cancer, prostate cancer, gastric cancer, malignant melanoma, lung cancer, and other malignant neoplasms." (PMID 29463039, 2018). "MMP family of proteinases, particularly MMP-1, MMP-2 and MMP-9 expressed in lung cancer, play an important role in malignant tumor metastasis." (PMID 28915603, 2017). "Combined our PPI network analysis with previous studies, PRAME knockdwon upregulates MMP1, CCL2, CTGF, and PLAU and contribute to lung cancer metastasis." (PMID 27391090, 2016). "In human lung cancer cells, the increased n-3 PUFA in fat-1-transfected cells resulted in reduced invasive properties due to down regulation of invasion-related genes, MMP-1 and integrin-α2." (PMID 21655218, 2011). "MMP1 is also known to be upregulated by hypoxia and HIF-1a in breast and lung cancer cells, and also by CXCR4 in Nk cells and prostate cancer cells." (PMID 20102637, 2010). "As examples of genetic polymorphisms that affect onset age of cancers other than that examined in this study, some reports discuss MMP-1 and DDB2 in lung cancer, and CCND1 in HNSCC and colorectal cancer." (PMID 17919326, 2007). "IR inhibited the proliferation, migration and invasive ability of CAFs in lung cancer, which might be related to the power of IR to promote MMP-3, inhibit MMP-1, and enhance integrins α2, β1 and α5 to stabilise lesion exposure." (PMID 38173726, 2023). "Furthermore, it has been reported that MMP1, HMGA2, TRPA1, and PLAU are highly expressed in various subtypes of lung cancer." (PMID 35354498, 2022). "Similarly, exosomes derived from lung CSCs promote EMT, migration, and invasion of lung cancer cells by upregulating the expression levels of N-cadherin, Vimentin, MMP-9, and MMP-1, and downregulating the expression of E-cadherin." (PMID 34511114, 2021). "Moreover, through Western blot analysis of lung cancer cells treated with lung CSC‐derived exosomes, we demonstrated that expression levels of N‐cadherin, vimentin, MMP‐9 and MMP‐1 were up‐regulated, whereas E‐cadherin expression was down‐regulated." (PMID 32396269, 2020). "MMP1 was the most significantly altered common signature gene shared across IPF and lung cancer." (PMID 33046043, 2020). "Furthermore, silencing FGFRL1 with siRNA promoted the migration and invasion of lung cancer cells and up‐regulated expression levels of N‐cadherin, MMP‐9 and MMP‐1, whereas E‐cadherin expression was down‐regulated." (PMID 32396269, 2020). "On the basis of their lung-tumorigenesis promoting functions, the MMP members MMP-1, MMP-2, MMP-7, MMP-9 and MMP-10 may result promising biomarkers for lung cancer." (PMID 29207990, 2017). "The expression of MMP-1 and VEGF is upregulated in 3D co-culture models compared to monoculture models, which demonstrates that the interactions between lung cancer cells and stromal cells may have a significant role in enabling and promoting metastasis." (PMID 27232698, 2016). "On the other hand, the studied polymorphisms in the MMP1 and MMP13 genes do not seem to influence the individual risk to develop lung cancer and survival time in our population." (PMID 19094243, 2008). "Similar to the 1G/2G polymorphism in the MMP1 promoter, the MMP13 G/G genotype presented a lack of association with lung cancer risk (adjusted OR = 1.23; 95% CI = 0.72–2.11)." (PMID 19094243, 2008).
lung carcinoma (continued). "Of these genes, MMP1 appeared to be the most promising driver gene showing significant differential expression in the transformation from healthy to IPF and NSCLC, supporting its potential as a novel therapeutic target for IPF, lung cancer, and IPF-progressed lung cancer." (PMID 33046043, 2020). "The overexpression of BTG2 may inhibit the growth and proliferation through inhibiting the protein expression of cyclin D1, and invasiveness through inhibiting the protein expression of MMP-1 (matrix metalloproteinase-1) and MMP-2 (matrix metalloproteinase-2) in the A549 human lung cancer cell line." (PMID 26132560, 2015). "Moreover, the MMP-1, MMP-2, MMP-9, and MMP-10 were found in the media of the ex vivo 3D lung model as well as in the serum of the blood samples collected from the superior vena cava and pulmonary veins of the lobectomy lung cancer specimens." (PMID 23028922, 2012). "Expression of MMP1 (collagenase), MMP2 (gelatinase), and MMP3 (stromelysin) transcripts was not significantly altered in lung cancer cells co-cultured with MSCs, but all three transcripts were downregulated in MSCs after co-culture with lung cancer cells." (PMID 33119681, 2020). "In lung cancer, PSAT1 can promote cell invasion by activating MMP1 pathway and was found as a novel predictor in stage I non-small cell lung cancer." (PMID 29297280, 2017). "In the 3D co-culture lung cancer model, simulated hypoxia and starvation conditions induced the secretion of VEGF, but not MMP-1." (PMID 27232698, 2016).
rheumatoid arthritis (86 papers, 2005 to 2026). A chronic, systemic autoimmune disorder characterized by inflammation in the synovial membranes and articular surfaces. "Both MMP1 and MMP13 are observed in the synovial fluid in pathologic situations such as cartilage breakdown, lymphocyte infiltration, and synovitis in OA, but MMP1 is also associated with rheumatoid arthritis, and MMP13 is the preferred therapeutic target for OA." (PMID 38613068, 2024). "Recent publications have investigated the potential role of the protein level of matrix metalloproteinase-1 (MMP-1) in the susceptibility to rheumatoid arthritis (RA) and osteoarthritis (OA)." (PMID 33331536, 2020). "AP-1 transcriptionally orchestrates cartilage-degrading matrix metalloproteinases (MMP1/MMP3) in the pathogenesis of rheumatoid arthritis." (PMID 40647090, 2025). "MMP1 was previously reported in painful joint pathologies, rheumatoid arthritis, and osteoarthritis." (PMID 39847262, 2025). "As well as inflammatory related diseases such as “Rheumatoid arthritis” (FDR = 1.6x10−09) with MMP1/3 and IL6." (PMID 37962736, 2024). "MiR-18a-5p increased the expression of MMP1, inflammatory cytokines and chemoattractant proteins in rheumatoid arthritis synovial fibroblasts through NF-κB dependent manner after TNFα stimulation." (PMID 35148687, 2022). "Oxidized LDL promotes MMP1 production in cultured synoviocytes derived from patients with rheumatoid arthritis." (PMID 35168639, 2022). "Our results that show that K exerts its anti NSCLC effects by inhibiting the MMP1 mediated IL-17 signaling pathway, rheumatoid arthritis pathway, and relaxin signaling pathway are consistent with our docking results and MD results." (PMID 35227278, 2022). "Similar effects of CSE on MMP1 were previously shown in periodontal ligament fibroblasts, in rheumatoid arthritis synovial fibroblasts, and in lung epithelial cells." (PMID 32569447, 2021). "These genes are involved in immune system regulation, some of which are associated with the host response to rheumatoid arthritis (CCL20, IL1A, and MMP1)." (PMID 33301474, 2020). "MMP1, a collagenase subfamily involved in the degradation of extracellular matrix, was upregulated in the rheumatoid arthritis pathway and IL-17 pathway in our study." (PMID 31988808, 2020). "As in chondrocytes, EGCG can also suppress the IL-1β-induced MMP-2 and TNF-α-induced MMP-1 and 3 production in rheumatoid arthritis synovial fibroblasts." (PMID 33374730, 2020). "In the bootstrap resampling, we selected several important rheumatoid arthritis genes such as MMP genes (MMP1, MMP3), CCL genes (CCL3, CCL4, and CCL26), and IL genes (IL6, IL8, IL19, and IL24)." (PMID 31371761, 2019). "Increased mechanical stress in rheumatoid arthritis results in a rapidly developing inflammation and elevated MMP1 and MMP13 expression, which can induce the degradation of cartilage and subchondral bone matrix." (PMID 30621194, 2019). "This is consistent with data in rheumatoid arthritis, where TH‐17 cells induced MMP‐1 and MMP‐3 production." (PMID 29210073, 2018). "The expression of CD147 is upregulated in the rheumatoid arthritis synovial membrane and correlates with MMP-1, MMP-2, and MMP-3 upregulation." (PMID 16207318, 2005). "Additionally, the KEGG pathway analysis showed 14 pathways (p < 0.05) related to potential targets, and CCL5, MMP3 and MMP1 were enriched in the rheumatoid arthritis pathway." (PMID 36615560, 2023). "TGF-β1 induced cytokines, such as TNF–α, IL-1β, IL-1 MIP-1α and MMP-1, in cultured fibroblast-like synoviocytes from rheumatoid arthritis (RA) and osteoarthritis (OA) patients." (PMID 40141345, 2025). "Elevated levels of the collagenase MMP1 have been observed in SF from patients with rheumatoid arthritis (RA)." (PMID 41013715, 2025). "This suggested the MMP-1 rs1799750 polymorphism maybe not contribute to the role of MMP-1 protein level in the risk of rheumatoid arthritis." (PMID 33331536, 2020).
rheumatoid arthritis (continued). "Elevated level of MMP-1 expression has been reported not only in rheumatoid arthritis (RA) but also in atherosclerotic plaques." (PMID 31447863, 2019). "In rheumatoid arthritis (RA), adipokines contribute to the inflammation process in the joint by inducing the expression of pro-inflammatory cytokines such as IL-6, IL-8, and MMP-1 in synovial fibroblasts and other synovial cells." (PMID 30208657, 2018). "In the case of osteoarthritis (OA) and rheumatoid arthritis (RA), members of the collagenase subgroup of the MMPs, specifically MMP-1 and MMP-13, are particularly important in the progression of joint disease." (PMID 19046432, 2008). "It has been found that NAMPT induce the expression of IL-6, matrix metalloproteinase 1 (MMP-1) and MMP-3 in synovial fibroblasts of rheumatoid arthritis." (PMID 39513038, 2024). "A notable aspect of this study was the impact of AG on MMPs, including MMP-1, MMP-3, MMP-8, and MMP-13, which are key targets in inflammatory arthritis, including OA and rheumatoid arthritis." (PMID 39125316, 2024). "In fibroblast-like synoviocytes from rheumatoid arthritis patients, silencing SOX5 decreased IL-6 expression and reduced MMP-1,-2, and -9." (PMID 36835058, 2023). "In joint inflammatory disease, synoviocytes expressed MMP1, MMP3, and MMP10 to increase their invasiveness to destruct the cartilage in rheumatoid arthritis." (PMID 37006258, 2023). "In vitro experiments have shown that the JBQG drug serum can inhibit the expression of cytokines (IL-6, IL-8, IL-22, IL-23), chemokine proteins and mRNA expression (MMP-1, MMP-2, MMP-3, MMP-9, MMP-13) in rheumatoid arthritis synovial fibroblasts (RA-FLS)." (PMID 37180723, 2023). "Genome-wide DNA hypomethylation is observed in rheumatoid arthritis synovial fibroblasts (RASF), resulting in the upregulated expression of 186 genes including MMP1 and MMP14." (PMID 33920915, 2021). "Andrographolide reduces MMP-1, MMP-3, and MMP-9 expression of rheumatoid arthritis fibroblast-like synoviocytes (RA-FLS) in hypoxia, decreasing HIF-1α expression and interfering with HIF-1α binding to DNA." (PMID 33374961, 2020). "HIF-1α acts as a key regulator during inflammation, increasing pro-inflammatory cytokines (e.g., TNF-α, IL-1β, IL-6, and IL-8), matrix metalloproteinases (e.g., MMP-1, MMP-3, and MMP-9), and pathways of glucose metabolism in rheumatoid arthritis (RA)." (PMID 33374961, 2020). "CCL5 induces collagen degradation by activating matrix metalloproteinase 1 (MMP-1) and MMP-13 expression in human rheumatoid arthritis synovial fibroblasts." (PMID 32630699, 2020). "Curcumin, another inhibitor of mTOR signaling, was also reported to alleviate rheumatoid arthritis-induced inflammation and synovial hyperplasia by reducing inflammatory mediators like IL-1β, TNF-α, MMP-1, and MMP-3." (PMID 32867828, 2020). "They concluded that treatments for rheumatoid arthritis which specifically target MMP-1 may limit the number of new joint erosion foci and thus improve the overall functional outcome for RA patients." (PMID 27478294, 2016). "Cordycepin inhibits interleukin-1β- (IL-1β-) induced matrix metalloproteinase-1 (MMP-1) and MMP-3 expressions in rheumatoid arthritis synovial fibroblasts (RASFs) and significantly inhibits AP-1 activation." (PMID 25587342, 2014). "Serum and synovial levels of MMP1, MMP3 and MMP13 are increased in rheumatoid arthritis and osteoarthritis." (PMID 24739658, 2014). "Of note, MMP-1 and MMP-3 have been known for their involvement in tissue destruction in rheumatoid arthritis and their expression in synovial fibroblast have been associated with the invasive ability of these cells." (PMID 21961038, 2011). "IL-1β increased the transcriptional and translational levels of MMP-1 and MMP-13 in rheumatoid arthritis FLSs, whereas the levels of MMP-2 and MMP-9 were unaffected." (PMID 17697361, 2007).
rheumatoid arthritis (continued). "Additionally, in synovial fibroblasts of rheumatoid arthritis, EGCG has been reported to inhibit the synthesis of matrix metalloproteinase-1 (MMP-1) and MMP-3 induced by TNF-alpha." (PMID 39997589, 2025). "In patients with OA, the immunoexpression levels of TNF-α, IL-1β, IL-7, MMP-1, MMP-2, and MMP-3 were significantly higher in patients with active rheumatoid arthritis (RA), whereas the immunoexpression levels of IL-1, IL-2, IL-4, IL-6, IL-15, IL-18, and MMP-3 were not statistically different." (PMID 40004793, 2025). "Although cipemast, an inhibitor of MMP-1, -3, and -9, was evaluated in osteoarthritis and rheumatoid arthritis, it failed to prevent joint degeneration." (PMID 41303525, 2025). "Besides, CD4+ IL-21+ cells sorted from the synovial fluid can induce fibroblast-like synovial cells to secrete MMP-1 and MMP-3, which promote inflammation and joint pathological changes in patients with rheumatoid arthritis." (PMID 37628716, 2023). "Furthermore, several genes that were annotated in studies on rheumatoid arthritis (VEGFA, TGFB2, MMP1, MMP3, IL8, CCL3L1, CTSL1, CCL2) were also significantly upregulated in the immature articular cartilage in our study." (PMID 27045355, 2016). "The production of chemokines (such as MCP-1, IL-8) is also increased in endothelial cells, rheumatoid arthritis fibroblast-like synoviocytes (RA-FLS) and mononuclear cells, as is the synthesis of RANK-L by RA-FLS, and that of MMP-1, MMP-3 and MMP-13 in chondrocytes." (PMID 25604317, 2015). "Similarly, TNFα-induced expression of matrix metalloproteinases (MMP1 and MMP3) in synovial fibroblasts from a rheumatoid arthritis patient was suppressed by P-Dex." (PMID 20836843, 2010). "Furthermore, BBR was shown to regulate the proliferation and adhesion of RA-FLS cells through the RAS/MAPK/FOXO/HIF-1 signaling pathway, as well as reduce the expression of matrix metalloproteinase (MMP)-1, MMP-3, RANKL, and TNF-α, thereby combating rheumatoid arthriti." (PMID 38957396, 2024). "RasGRP4 is expressed in fibroblast-like synoviocytes (FLS) in rheumatoid arthritis (RA) patients, elevating the FLS proliferation and MMP-1 production." (PMID 36817422, 2023). "Therefore, the expression of MMPs, such as MMP-1 and/or MMP-9, can be epigenetically regulated in multiple diseases influenced by HDACs including inflammatory conditions such as rheumatoid arthritis, bacterial infections, and cancer metastasis." (PMID 33920915, 2021). "Discovery of the interstitial collagenase (MMP-1) and its role in tissue destruction, such as in rheumatoid arthritis (RA), raised the question of the cellular source for this enzyme." (PMID 29848388, 2018). "Matrix metalloproteinases-3 (MMP-3), a member of the matrix metalloproteinases, can degrade extracellular proteoglycans and type IV collagen; activate the activities of MMP-1, MMP-8 and MMP-9; accelerate articular cartilage aging; and exacerbate osteoarthritis (OA) and rheumatoid arthritis (RA)." (PMID 38667174, 2024). "Interestingly, MMP-1 (or collagenase-1) and/or MMP-13 (or collagenase-3) are among the enzymes expressed by human chondrocytes in degenerative pathologies of cartilage, namely osteoarthritis and rheumatoid arthritis and are thus thought to play a critical role in cartilage destruction." (PMID 20193091, 2010). "Bone marrow CD34+ cells from rheumatoid arthritis (RA) patients have abnormal capacities to respond to tumor necrosis factor (TNF)-α and to differentiate into fibroblast-like cells producing matrix metalloproteinase (MMP)-1." (PMID 16519794, 2006). "Cipemastat, which inhibits MMP-1, MMP-3, and MMP-9, was used for the treatment of rheumatoid arthritis and osteoarthritis, but it was not shown to prevent the progression of joint damage in patients." (PMID 33419373, 2020).